STAT1 (signal transducer and activator of transcription 1)
Diseases named in the same sentence as STAT1 in open-access papers (continued):
Sharing a sentence is not in itself a finding about the gene and the disease.
cancer (continued). "Since IRF-1 is a central modulator of the expression of the CXCR3 ligand chemokines, this study reinforces the relevance of the IFN-γ/STAT-1/IRF-1 axis as a favorable prognostic factor in cancer." (PMID 21875439, 2011). "STAT1 is best known for its pro-apoptotic role in response to interferons, but STAT1 has also been reported to have a pro-survival role in some cancers." (PMID 20098684, 2010). "We propose that overexpression of the IFN/STAT1 pathway contributes to therapy resistance and metastatic propensity leading to the poor response to traditional cancer therapy observed in patients with metastatic disease." (PMID 19503789, 2009). "The statuses of p-Stat1 (Tyr701) and p-Stat5 (Tyr694) in the cancer cell lines were also examined using Western blot analysis." (PMID 17311011, 2007). "In addition to IFN-γ response-associated genes (JAK1, STAT1 and STAT3), CIITA, a master regulator of MHC-II gene expression, was highly expressed in MHC-II+ cancer cells." (PMID 41281745, 2025). "Two additional factors that may lead either to apoptosis or survival of cancer cells have been found to increase, and are STAT1 and WNK1." (PMID 41515132, 2025). "Selective AKTS473 activation could support cancer cell survival and metabolic adaptation, while STAT1 hyperactivation might facilitate immune evasion and survival under inflammatory conditions." (PMID 41034404, 2025). "Interestingly, Western blotting showed increased p-STAT1 and p-STAT2 levels in THP1-MΦ cocultured with IFN-β–treated USP5-deficient cancer cells." (PMID 41321309, 2025). "Notably, nuclear STAT1 expression, indicative of protein activation, was rare in cancer samples but correlated with poor prognosis." (PMID 41367865, 2025). "Our data support that STAT1 is upregulated as cervical lesions progress to cancer and suggest that STAT1 may serve not only as a prognostic marker for lesion development but also as a therapeutic target." (PMID 41367865, 2025). "The function and significance of STAT1 in cancer biology have been studied for a long time." (PMID 40407590, 2025). "Moreover, it has been demonstrated that acidosis in the TME—alongside the accumulation of lactate—upregulate PD-L1 on cancer cells via the activation of STAT1 (IFN-γ/eIF4F pathway) and STAT3, facilitating immune evasion." (PMID 41375084, 2025). "Kyoto Encyclopedia of Genes and Genomes (KEGG) analysis revealed the involvement of various immune response, cancer, and signal transduction pathways, including cytokines and cytokine-receptor interactions, which differed between STAT1-∆N-expressing NHL cells and normal WT cells." (PMID 40287766, 2025). "Low pH also facilitates resistance to ICIs by enhancing PD-L1 expression on cancer cells through acidosis-mediated STAT1 activation, suppressing effector T-cell function, and fostering an immunosuppressive TME dominated by exhausted T-cells and pro-tumourigenic macrophages." (PMID 41375084, 2025). "Furthermore, knockdown of LC3B in cancer cells substantially decreased the secreted–p-STAT1/2 and EGFP+ THP1-MΦ subpopulation." (PMID 41321309, 2025). "Future functional studies could provide insights into the role of STAT1 in cancer biology by investigating how rs190542524 and rs114360225 affect its function at the molecular level." (PMID 40407590, 2025). "Additionally, the data suggest potential new therapeutic targets, such as TOP2A, CDCA7, and STAT1, for future investigations against this aggressive form of cancer." (PMID 40732340, 2025).
cancer (continued). "Validation by qPCR confirmed the strong down-regulation of Oasl2 in both brain regions, which is in good agreement with in vitro data demonstrating a strong reduction in Oasl2 expression levels upon STAT1 short interference RNA treatment of NIH-CUG2 cancer cells." (PMID 40597232, 2025). "Previous research on the role of STAT1 subtypes in cancer has been relatively limited." (PMID 40849492, 2025). "Given the effectiveness of targeting PRMT1 in reducing persistence in STAT1-high cancer cells, we reasoned that genetic alterations in the STAT1 pathway could provide clues for patient stratification." (PMID 39699269, 2025). "Two of the last hub genes, MITF and STAT1 are involved in human cancers." (PMID 39820173, 2025). "Additionally, a correlation of STAT1 expression in cancer patients tends to have a better clinical prognosis, including colon-rectal cancer, soft tissue sarcoma, metastatic melanoma, hepatocellular carcinoma, and pancreatic cancer." (PMID 38990440, 2024). "STAT3 and STAT5A/B can promote cancer development, whereas STAT1 is a cancer suppressor." (PMID 38318160, 2024). "STAT1 has been reported to have both cancer-promoting and cancer-suppressing properties." (PMID 39525474, 2024). "Nonetheless, their finding solely showed that the αvβ6 integrin has profound effects on the microenvironment by preventing induction of the STAT1/MX1/2 signaling pathway in donor cancer cells and their exosomes, and the investigation of exosomal αvβ6 integrin in PCa patients was not conducted." (PMID 39538297, 2024). "Considering these cytokine array results, the differences in GAS-NK activation levels among co-cultured cancer cells may stem from variations in the production of cytokines related to STAT1 signaling activation." (PMID 39349746, 2024). "Finally, the mechanism of TGFBR2 in regulating the phosphorylation of STAT1 to suppress BC cancer development should be validated." (PMID 39525474, 2024). "STAT1 inhibits T cell exhaustion and myeloid derived suppressor cell accumulation; thus, the selective induction of STAT1 phosphorylation in cancer patients could potentially improve antitumor immune responses." (PMID 38561388, 2024). "However, one potential limitation of this cell-based therapeutic is that IFN-γ released from activated NK cells can induce STAT-1-dependent expression of NK cell inhibitory ligands on the surface of the cancer cells being targeted for NK cell killing." (PMID 39205244, 2024). "Therefore, it is possible that the decline of epidermal EGFR-mediated STAT3 signaling switches the balance in favor of STAT1 activation as it is described for STAT3 knockout conditions in various model systems including cancer cells." (PMID 39521937, 2024). "Moreover, cancer cells often exhibit an increased expression of STAT1/2 and IRF9 for various reasons." (PMID 39062738, 2024). "However, reflecting the context-dependency of all STATs, STAT1 was also found to act as a cancer promoter in a mouse model of leukemia." (PMID 38611065, 2024). "This may be due to inactivation of the STAT1 cell death response in aggressive cancer cells, leaving only the pro-tumorigenic response intact." (PMID 39345336, 2024). "STAT1 is a known oncogene in many cancers including endometrial cancer." (PMID 39009698, 2024). "As addressed previously, IFNγ mainly secreted by CD8+ T cells and NK cells, could induce dormancy and G0/G1 growth arrest in cancer cell via STAT1 signaling." (PMID 38216787, 2024). "However, an increasing number of recent studies have found that STAT1 is an oncogene in many cancers." (PMID 38385074, 2024). "It remains to be seen whether enhancing STAT1 activity will be a worthwhile addition to anti-cancer therapy." (PMID 38611065, 2024). "Moreover, KO cells demonstrated substantially altered transcription factor motifs, e.g., Stat1, Stat2, and Irf/Nfkb, suggesting enhanced cancer immunogenicity at the epigenetic level." (PMID 39255035, 2024).
cancer (continued). "While triptolide could down-regulate PD-L1 expression in cancer cells by inhibiting Jak2/STAT1 pathway, which helped to inhibit tumor growth and metastasis in cancer treatment." (PMID 37497002, 2023). "In addition, the distribution of STAT1, STAT2, STAT3, STAT4, STAT5A, STAT5B, and STAT6 expression in CD8+ T cells in pan-cancer were displayed, which presented that STAT1 and STAT2 had prominent up-regulation in CD8+ T cell with ISG IFIT1." (PMID 36968603, 2023). "Furthermore STAT1 activation can be a key component of enhancing the immunogenicity of cancer cells by upregulating cell surface expression of histocompatibility proteins and other co-stimulatory molecules." (PMID 38022653, 2023). "In a mouse model of RCC, lenvatinib treatment inhibits both EGFR and FGFR signaling, and could restore the IFNγ-STAT1 signaling pathway and consequently prove the anti-cancer effect of the inhibitor." (PMID 37190141, 2023). "Most studies to date have shown that STAT1 has a significant inhibitory effect on malignant tumors." (PMID 36899018, 2023). "However, many studies have shown contradictory observations, that is, STAT1 and/or p-STAT1 play a role as a cancer promoter in some malignancies and are negatively correlated with patient survival." (PMID 36899018, 2023). "Studies have shown that JAKs-STAT1 signaling pathway may be regulated by m6A at the transcriptional level, resulting in aberrant signaling in cancer progression." (PMID 37334368, 2023). "Moreover, MBZ can modulate various cancer-associated pathways, including MAPK14, MEK-ERK, C-MYC, USP5/c-Maf, TNIK, XIAP, ELK/SRF, NFKB, MYC/MAX, E2F/DP1, TGF/SMAD, AP1, and STAT1/2, dependent on the specific cancer model." (PMID 36674870, 2023). "Moreover, due to the deficiency in our understanding of STAT1, STAT2, STAT4, and STAT6 in cancer, selective inhibitors also remain elusive." (PMID 37173951, 2023). "IFNγ-mediated PD-L1 activation in various cancers occurs via STAT1 phosphorylation." (PMID 37316937, 2023). "Knockdown of STAT1 expression inhibited the proliferation and colony formation ability of DU 145 and PC-3 cells, while inhibiting apoptosis, and these results conferred STAT1 typical characteristics of cancer-promoting factor." (PMID 36899018, 2023). "IFN-α-induced p-STAT1 was impaired in B, T and NK cells from all cancer groups." (PMID 37741983, 2023). "Finally, our study suggests the therapeutic potential of targeting the STAT1/HMGB1/NF-κB signaling axis for the prevention of chronic kidney problems after cisplatin treatment in cancer patients." (PMID 37284446, 2023). "It was also observed that TNF-α, CASP8, CLIP3, and STAT1 are characteristics of G2 and G3 cancer." (PMID 37233761, 2023). "Cancer plasticity is a newly recognized hallmark of cancer and induced or regulated not only by a vaste array of transcription factors, by the EMT-specific ones but also by less specific ones such as HIF1A or STAT1/2." (PMID 36754910, 2023). "Alternatively, reactivation of STAT1-mediated immune signaling in CIN+ cancers could provide a strategy to selectively treat aneuploid cancers." (PMID 37561163, 2023). "Moreover, we identified that IL-11 derived from cancer cells at least partially inhibits the expression of GPR84 in OCPs by inactivating STAT1." (PMID 36593458, 2023). "Interestingly, the G-MDSC subset, known from autoimmune pathologies and cancer immunology to actively suppress T cell responses, was found diminished in this cohort of STAT1 GOF patients, presenting another possible module of immunoregulatory failure." (PMID 37358695, 2023). "Moreover, we identified MDSC secreted IL-6/IL-10/IL-1β induced STAT1/STAT3/NF-κβ signaling axis as a targeted cascade to promote early drug resistance in cancer cells." (PMID 38304256, 2023). "However, we demonstrated that STAT1 is another downstream target of IL-11 in the regulation of cancer metastasis." (PMID 36593458, 2023).
cancer (continued). "The authors suggested that targeting the IFN/STAT1 signaling pathway, EGFR ligands, and related genes could serve as novel predictors of efficacy in KRAS mutations in cancer patients on cetuximab treatment." (PMID 36765706, 2023). "Interestingly, in some cancer cells, STAT1 can negatively regulate ERBB2/Neu-dependent transformation." (PMID 37669313, 2023). "Furthermore, it has been suggested that cancer cells with STAT1 activation act as leader cells to drive the polyclonal collective invasion of skin SCC." (PMID 35606369, 2022). "Notably, a previous study showed that cANGPTL4 regulates cancer-cell proliferation and that STAT1 induction is dependent on the NADPH oxidase-mediated production of superoxide (O2−), as well as on the Src and mitogen-activated protein kinase (MAPK) pathways." (PMID 35328637, 2022). "Furthermore, immunohistochemical analysis of STAT1 protein in the tissue microarray of skin SCC revealed that STAT1 is notably expressed in the invasive front of cancer cell clusters during collective invasion." (PMID 35606369, 2022). "Apigenin, a flavonoid derived from onions, oranges, or chamomile tea, can attenuate IFN-γ- or IFN-β-induced PD-L1 upregulation in cancer cells by blocking the signal transducer and activator of the transcription 1 (STAT1) pathway, resulting in enhanced T-cell-mediated cancer cell death." (PMID 36015215, 2022). "The involvement of the IFN-γ/Jak1/STAT1 signaling pathway in ferroptosis therefore provides additional opportunities for cancer therapy, as some reagents targeting this pathway could be applied." (PMID 35399527, 2022). "All these demonstrate that IFN-γ activates MDK via STAT1 in cancer cells." (PMID 35747815, 2022). "Low concentrations of IFN-γ boost CSC stemness through the activation of the PI3K/AKT/NOTCH1 pathway, whereas high levels of IFN-γ induce cancer cell apoptosis through the janus kinase 1 (JAK1)/signal transducer and activator of transcription 1 (STAT1)/caspase pathway." (PMID 36032082, 2022). "Given the functional connection between STAT1 and type I PRMTs in modulating cancer persistence, we hypothesized that PRMTi could be effective in reducing persisters even without exogenous IFNγ stimulation." (PMID 35089788, 2022). "It is known that lncRNA PLAC2 inhibits cancer progression by interacting with STAT1 and RPL36." (PMID 35475470, 2022). "Indeed, higher expression of p38, JNK, and MEK1 was found in samples of patients with cancer cachexia as well as increased levels of transcription factors, such as STAT-1." (PMID 36078078, 2022). "The results showed that downregulation of STAT1 attenuated the anti-cancer effects of 125I and EPI." (PMID 35692770, 2022). "However, studies that relate cancer development to aberrant activation of STAT1 have blown-up over the last few years, the abnormal expression of STAT1 being now even used as a prognostic factor for patients with solid tumors." (PMID 35163491, 2022). "We hypothesized that EPI would enhance the anti-cancer effects of 125I seeds via the JAK/STAT1 signaling pathway." (PMID 35692770, 2022). "Therefore, the impact of STAT1 on cancer is not yet fully understood because the role of STAT1 varies among cancer cell types and situations." (PMID 35606369, 2022). "Based on these findings, we suggest that the EPI-induced enhanced anti-cancer effects of 125I seeds might be mediated by the JAK/STAT1 signaling pathway." (PMID 35692770, 2022). "Our recent drug screen and functional assay identified HSP90 as a universal control of the protein stability of nuclear transcription factor STAT1 in a variety of different cancer cells, thereby promoting subsequent gene expression of immune checkpoint molecules (IDO1 and PD-L1)." (PMID 35479647, 2022). "Another example can be found in another study that contradicted the roles of STAT1 in cancer." (PMID 35158821, 2022). "STAT1 is also a key player in cancer cell apoptosis and has crosstalk with XiaP." (PMID 35475470, 2022).
cancer (continued). "Some studies have mentioned that the expression levels of STAT1 and pSTAT1 in specific cell types could be prognostic markers for cancer progression." (PMID 35406434, 2022). "Furthermore, higher expression of STAT-1 was observed in the adipose tissue of these patients compared to cancer patients with stable weight." (PMID 36078078, 2022). "In addition, Western blot analysis showed decreased SOCS1, but increased phosphorylated STAT1 (p-STAT1)/p-STAT3 ratios in miR-155–overexpressing primary cancer cells compared with controls." (PMID 35925680, 2022). "We tested whether PRMTi could reduce persisters from cancer cells with high endogenous STAT1 expression." (PMID 35089788, 2022). "In addition, STAT1 knockdown experiments showed that PTH-AS regulates cancer characteristics along with the expression of various genes, including IRDS, through STAT1 upregulation." (PMID 35618021, 2022). "Furthermore, we showed that pharmacological inhibition of STAT1 with Fludarabine (currently employed clinically for cancer therapy) coupled with dexamethasone (DEX) treatment significantly reduced disease severity." (PMID 35280986, 2022). "It interferes with functional NF-κB activation in different carcinoma cell lines and it can contribute to the development of EBV-associated tumors and their progression by activating AP-1 and signal transducer and activator of transcription 1 (STAT1) and inhibiting TGF-β1." (PMID 35935191, 2022). "We observed the upregulated expression of STAT1 in the alisertib-treated cancer cells." (PMID 34522170, 2021). "The IFN/STAT1 pathway functions as a double-edged sword in cancer development." (PMID 33807608, 2021). "Among CD68+CD163+ TAMs also expressing the recently identified TREM2 marker, we could identify a CXCL10+IRF1+STAT1+ M1-type Mφ population (Cluster 9) shared between all cancer types." (PMID 34220848, 2021). "We have also revealed that the VAV2-STAT1 axis can be targeted by STAT1 inhibitor to enhance radiosensitivity of cancer overexpressing VAV2, which might have an important implication in developing more effective and precision cancer radiotherapy." (PMID 34462423, 2021). "Also, a series of in vitro experiments suggests that ELF-1- and/or STAT1-dependent Lin28b regulation is responsible for Let-7 induction in Fhit-expressing cancer cells." (PMID 33437205, 2021). "Signal transducer and activator of transcription 1 (STAT1) is part of the Janus kinase (JAK/STAT) signaling pathway and mediates important events associated with mucosal homeostasis, intestinal immune function, and cancer progression." (PMID 34299314, 2021). "Practically, there are two-faced effects of STAT1 on tumorigenesis in different kinds of cancers." (PMID 33834023, 2021). "Stat1 overexpression has also been reported in many cancer types." (PMID 34685622, 2021). "In addition, down-regulation of PKR and STAT1 mRNA levels was also observed in KRAS mutant cancer cells when combined treatment performed." (PMID 34578339, 2021). "In other cancers, STAT1 emerges as a suppressor of metastasis." (PMID 34638338, 2021). "This might suggest that inhibition of apoptosis via inducing Mcl-1 expression protects cancer cells from stress in Stat1-overexpressing cells." (PMID 34685622, 2021). "Likewise, increased activity of STAT1 has been found in CAFs which enhance the proliferation and survival of cancer cells." (PMID 34921160, 2021). "Interestingly, STAT1 activation has been observed in untransformed and cancer cell lines where aneuploidy was induced by continuous exposure to reversine (F. Foijer, personal communication)." (PMID 34105235, 2021). "In summary, the exposure of cancer cells to alisertib induced the upregulation of STAT1 in association with the lack of methylation on the promoter region of this gene." (PMID 34522170, 2021). "Consequently, dendritic cell (DC) antigen presentation was inhibited, suggesting that STAT1 nitration mediates MDSCs’ inhibitory effects on immune cells during cancer." (PMID 34299314, 2021).